GIP (gastric inhibitory polypeptide)
Diseases named in the same sentence as GIP in open-access papers (continued):
Sharing a sentence is not in itself a finding about the gene and the disease.
Obesity (continued). "A study of 31 adults with obesity due to MC4R deficiency indicated that tirzepatide, a dual GLP-1 and glucose-dependent insulinotropic polypeptide (GIP) receptor agonist, may be a particularly effective therapeutic strategy." (PMID 41489710, 2026). "The advancement of multi-receptor drugs that mimic the glucagon-like peptide-1 (GLP-1), glucose-dependent insulinotropic polypeptide (GIP) and glucagon action, including semaglutide, tirzepatide, and retatrutide, has driven the pharmacotherapy of obesity to a new era of effectiveness." (PMID 41596421, 2026). "Incretin-based obesity treatments-glucagon-like peptide-1 receptor agonists (GLP-1 RAs) and dual glucagon-like peptide-1 receptor/glucose-dependent insulinotropic polypeptide receptor agonists (GIP/GLP-1 RAs or dual agonists)-are a major stride in the evolution of obesity management." (PMID 41598480, 2026). "Importantly, modified forms of two of these hormones – GLP-1 and GIP – are now widely used as drugs to treat diabetes and obesity." (PMID 41542598, 2026). "In this narrative review, we synthesize current evidence on classical incretins and less frequently examined gastrointestinal hormones—including PGDP beyond GLP-1 and GIP, as well as orexigenic and anorexigenic peptides—comparing individuals with obesity or T2DM with healthy controls." (PMID 41575482, 2026). "GIP has an anabolic effect on adipose tissue, promoting subcutaneous fat deposition while also enhancing the release of pro-inflammatory cytokines from adipose tissue—disturbances commonly observed in obesity." (PMID 41575482, 2026). "GIP also plays a role in lipid metabolism by promoting lipid storage and adipogenesis, and therefore, microbial-induced changes in GIP activity can influence adiposity, potentially aiding in the reduction of body fat and the prevention of being overweight and even obesity." (PMID 39896730, 2025). "With the increasing use of GLP-1/GIP agonists for both diabetes and obesity, it is imperative for clinicians to include these agents in the differential diagnosis when evaluating new-onset GI symptoms, particularly in patients without a history of abdominal surgery." (PMID 40978855, 2025). "There is still a lot of crucial research that must be undertaken, but there has been great progress regarding further understanding the links between metabolic peptides like GLP-1, GIP, and PP, as well as their agonists and properties, in order to combat obesity and neuroinflammation." (PMID 39857716, 2025). "The anti-obesity effect of GIP is likely exerted primarily through ARC in the brain." (PMID 39940910, 2025). "Notably, elevated circulating GIP concentrations have been reported in individuals with obesity compared with healthy controls." (PMID 41228499, 2025). "Long-lasting GIP agonists reportedly reduce body weight in mice with HFD-induced obesity." (PMID 39940910, 2025). "Patients with obesity and co-occurring type 2 diabetes may benefit from an antidiabetic medication known to promote weight loss, such as a GLP-1R agonist or GIP/GLP-1R dual agonist." (PMID 40568728, 2025). "Clarifying these central mechanisms is crucial, as the brain plays a vital role in regulating energy balance, and understanding how GIP affects central pathways to modulate food intake will be invaluable for improving GIP-based therapies for obesity and diabetes treatment." (PMID 40166681, 2025). "At the time we started the pharmacological treatment of these patients, affected by both insulin resistance and obesity, no other GLP-1 RA or agonist of both GLP-1 and glucose-dependent insulinotropic polypeptide (GIP) with an indication for obesity treatment were available in Italy." (PMID 40710038, 2025). "Ablation of GIP-producing cells in mice reduced HFD-induced obesity." (PMID 39940910, 2025). "GIP is involved in the regulation of lipid metabolism and the onset of obesity." (PMID 40649920, 2025).
Obesity (continued). "In a study performed on whether the inhibition of GIP signaling prevents obesity, researchers found that an excessive accumulation of fat allows for the hypersecretion of GIP." (PMID 39857716, 2025). "Tirzepatide, a dual GLP-1 (Glucagon-Like Peptide-1)/GIP (Glucose-Dependent Insulinotropic Polypeptide) receptor agonist, has demonstrated unprecedented efficacy in obesity and diabetes, alongside pleiotropic actions on inflammation, fibrosis, and adipose remodeling." (PMID 41226777, 2025). "Tirzepatide is a novel dual GIP/GLP-1RA that has revolutionized obesity management." (PMID 39857719, 2025). "Exaggerated nutrient-stimulated GIP secretion is also observed in obese leptin-deficient ob/ob mice and in humans with obesity [481,], but this has not been confirmed by other studies [492,]." (PMID 40024571, 2025). "Furthermore, it discusses the potential anti-obesity effects of dual agonists targeting both the glucose-dependent insulinotropic polypeptide (GIP) receptor and the GLP-1 receptor, which have gained attention in recent years." (PMID 40607142, 2025). "While advances in GLP-1 and GIP agonists are promising, long-term outcomes remain uncertain, and current data continue to position bariatric and metabolic surgery as the gold standard for treating severe obesity with complex multi-morbidity." (PMID 40381136, 2025). "Increased levels of GIPR expression in the ARC may contribute to increased GIP action in the ARC and may be considered a mechanism to reduce food intake through the GIP in obesity." (PMID 39940910, 2025). "Nevertheless, GIP receptor antagonism is thought to exert beneficial metabolic effects due to the expression of GIP receptors on adipocytes, along with elevated circulating GIP levels observed in both individuals with obesity and individuals given a high-fat-diet." (PMID 40469445, 2025). "Nutritional and metabolic interventions—including weight reduction, GLP-1 receptor agonists, dual GLP-1/GIP agonists, and bariatric/metabolic surgery—demonstrate renoprotective effects in obesity-related kidney disease and may have implications for IgAN." (PMID 41156559, 2025). "In both groups, GIP and aGLP-1 correlated with decreased hunger (p < 0.0001, p = 0.001) and (p < 0.0001, p < 0.05), along with increased satiety in controls (p < 0.0001, p = 0.001) and people with obesity (p = 0.049, p = 0.01)." (PMID 40961390, 2025). "Adults with T1D who had participated in the “Uncovering Rare Obesity” program (through which eligible subjects were tested for genetic forms of obesity) and used incretin analogs (including GLP-1 RAs and the dual GIP/GLP-1 RA tirzepatide) for the management of obesity were enrolled in this study." (PMID 40004833, 2025). "In people living with obesity and T2D, plasma levels of intact GIP after breakfast, lunch and dinner are, as expected, increased in individuals receiving DPP4 inhibitors (saxagliptin, sitagliptin or vildagliptin) relative to those receiving placebo, but this does not reflect increased secretion." (PMID 40024571, 2025). "Resolution of obesity is seen in GIP-reduced mice under HFD conditions." (PMID 39940910, 2025). "The hypothesis suggests that tirzepatide's dual GIP and GLP‐1 agonism creates a potent metabolic effect that could be leveraged to treat obesity by promoting fat loss and improving insulin sensitivity." (PMID 39540705, 2025). "Furthermore, prandial GIP levels are elevated in patients with T2D and obesity and are positively correlated with obesity." (PMID 40507574, 2025). "In individuals with obesity, GIP levels are often elevated, which may worsen IR commonly observed in patients with T2D." (PMID 40806228, 2025). "Consequently, the intergroup disparity in serum GIP concentrations likely mediates, at least in part, the divergent anti-obesity potency of WPI versus SPI." (PMID 41228499, 2025).
Obesity (continued). "GIP and GLP-1 dual agonists, such as Mounjaro, enable insulin secretion through activation of β-cell GIP receptors and appear to greatly enhance the satiety and weight loss encountered with GLP-1R activation alone, aiding obesity." (PMID 39519546, 2024). "GIP is markedly higher in leaner individuals and is upregulated after a high-fat meal, while C-peptide and its overall AUC after a high fat meal ingestion is markedly elevated in people with obesity compared with lean subjects." (PMID 38762719, 2024). "Prompted by these recent studies, we tested the hypothesis that strategies aimed at enhancing the release of endogenous GIP from K cells might prove beneficial for the treatment of T2D and obesity-related metabolic disorders." (PMID 39436694, 2024). "In addition, specific destruction of GIP-secreting K-cells in mice also safeguards against diet-induced obesity and ameliorates insulin resistance." (PMID 38861364, 2024). "Subsequently, GIP was shown to improve insulin sensitivity and reduce food intake, actions supporting the development of GIP-based multiagonists for the treatment of people with T2D and obesity." (PMID 39723966, 2024). "The new anti-obesity drugs, semaglutide, a GLP-1 receptor agonist, and tirzepatide, a dual GIP and GLP-1 receptor agonist, have demonstrated remarkable efficacy for weight loss and hold great promise as anti-obesity treatments to alleviate metabolic dysfunction." (PMID 39056292, 2024). "More recently, clinical trials involving drugs that combine GLP-1 receptor agonism with agonism or antagonism of other receptors, such as those for GIP or glucagon, have shown considerable promise in the management of T2D and obesity (eg, the triple GLP-1/GIP/glucagon RA, retatrutide)." (PMID 39568409, 2024). "GIP-induced TG uptake into AT may be dependent on the level of AT insulin resistance, which can enhance obesity and T2DM conditions." (PMID 38579777, 2024). "It has been suggested that inhibiting GIPR activity and endogenous GIP may be effective in treating obesity, particularly when it is diet-induced through a high-fat diet." (PMID 39408213, 2024). "However, the authors emphasize the need for further studies to understand the precise mechanisms of GIP action in obesity." (PMID 39408213, 2024). "Similar to GLP-1, impaired GIP secretion is also expected in adults with obesity and T2D." (PMID 38087928, 2024). "From currently available obesity pharmacotherapy, GLP-1 agonist (or combined GLP-1 and GIP agonist) data offer the most promising weight loss, body composition and safety outcomes in older adults; however, more research on muscle/bone mass preservation is needed." (PMID 39514148, 2024). "As a matter of fact, obesity appears to generate resistance for the effects of GIP in AT: GIP-R density and GIP activity reduce in obese subjects, whereas they may increase after weight loss." (PMID 39201336, 2024). "In study 1, we show that both fasting and postprandial GDF15 levels are unaffected by weight status in healthy individuals, whereas the levels of GIP are markedly elevated in leaner individuals compared with people with obesity and are robustly increased following a high-fat meal." (PMID 38762719, 2024). "It is possible that the high basal level of GIP observed in our study may be explained by resistance to endogenous GIP in obesity." (PMID 39598143, 2024). "Furthermore, a dual agonist GLP-1/gastric inhibitory polypeptide (GIP) RA named tirzepatide has recently been approved in several countries for the treatment of diabetes and is being considered for approval for obesity and weight management." (PMID 38298102, 2024). "It is not clear if antagonizing the GIP (glucose-dependent insulinotropic polypeptide) receptor (GIPR) for treatment of obesity is likely to increase the risk of fractures, or to lower bone mineral density (BMD) beyond what is expected with rapid weight loss." (PMID 38118020, 2024).
Obesity (continued). "The rise of GIP from enterogastrone to major metabolic hormone makes an interesting story, but the answer is largely due to the well-known insensitivity of humans with obesity and obesity-driven T2DM to the insulinotropic and glucose-lowering actions of GIP." (PMID 38861364, 2024). "Medications such as glucagon-like peptide 1 (GLP-1) agonists, glucose-dependent insulinotropic polypeptide (GIP) agonists, and dual GLP-1/GIP agonists could benefit patients with diabetes, obesity, and cardiovascular disease." (PMID 37521420, 2023). "Studies using GIP receptor knockout mice suggest that GIP action is important in fat deposition and that inhibition of GIP signaling may be a target for obesity." (PMID 37442561, 2023). "Regarding future obesity treatment strategies implementing novel GIP/GPL-1 co-agonists that are emerging it is unclear whether every co-agonist will be as beneficial as and superior to single GLP-1R agonism." (PMID 37592302, 2023). "In addition, clinical trials of tirzepatide, a dual GIP/GLP-1R agonist, have reported a weight loss of up to 20%, providing new hope that obesity and its related co-morbidities can be managed with medication rather than surgical interventions." (PMID 36834794, 2023). "Recently the dual agonist of GLP-1RA/glucose-dependent insulinotropic polypeptide (GIP) (Tirzepatide) has been found to improve glycaemic control and reduce weight in patients with T2D and severe obesity and in patients with severe obesity to reduce weight by up to 20% after a 72 week study period." (PMID 36670155, 2023). "In obesity settings, the inhibition of endogenous GIP or its receptor leads to negative energy balance and reduced adiposity, and paradoxically, a similar effect is obtained after administration of exogenous GIP agonists." (PMID 36010335, 2022). "Elevated glucose-dependent insulinotropic peptide (GIP) levels in obesity may predict the metabolic benefits of n-3 PUFA supplementation." (PMID 36010335, 2022). "Besides GIP receptor expression on adipocytes, other indications for a link between GIP and obesity include the findings of increased circulating GIP levels in both obese individuals and subjects given a high‐fat diet (HFD)." (PMID 35710141, 2022). "SGLT1 protein expression and is response to GIP appears to decrease during obesity at nine months." (PMID 35224107, 2022). "GIP promotes fat deposition in adipose tissue, and contributes to fat‐induced obesity." (PMID 35452190, 2022). "Determining whether such a regulatory circuit between HNF4A and GIP is of functional importance in normal and diseased individuals with obesity requires further investigation." (PMID 35017517, 2022). "Our results support the development of GIP antagonists for the therapy of obesity." (PMID 35710141, 2022). "Although the insulinotropic activity of GIP has now been confirmed in human studies involving a GIP receptor (GIPR) antagonist, whether GIP contributes to the development of obesity remains controversial." (PMID 34713962, 2022). "Enhanced GIP signaling seems to be closely associated with fat‐induced obesity, independent of hyperinsulinemia." (PMID 35452190, 2022). "Unlike GLP‐1, plasma GIP levels rise immediately after oral carbohydrate and fat consumption, causing obesity in the event of an overdose." (PMID 35452190, 2022). "Further, human obesity correlates with hypersecretion of GIP." (PMID 34260412, 2021). "Chronic reduction in GIP secretion reduces obesity and insulin resistance in high-fat fed mice." (PMID 34660576, 2021). "Hypersecretion of GIP in obesity may work as a compensatory mechanism; however, despite higher concentration, GIP cannot account for the hyperinsulinemia of obesity through its insulinotropic action." (PMID 33503878, 2021). "Xenin is known to potentiate the actions of GIP, and in addition to positive glycaemic outcomes, through reduced appetite and augmented insulin secretion, the peptide also restored GIP sensitivity that is dampened in obesity." (PMID 34093449, 2021).
Obesity (continued). "The use of genetic animal models has suggested that GIP promotes obesity." (PMID 34260412, 2021). "Animal models with diminished GIP activity including Gipr knockout mice, enteroendocrine K-cell ablation, and GIPR antagonism show reduced body weight gain associated with diet-induced obesity." (PMID 33803183, 2021). "Compared to a selective GLP-1 receptor agonist, the synergistic action of GIP combined with GLP-1 shows more effective weight loss and reduction in food intake with increased energy expenditure in genetic mouse models with diet-induced obesity." (PMID 34577569, 2021). "GIP has been proposed as one of the links between overfeeding and obesity." (PMID 33503878, 2021). "In addition, knock-in of a biologically inactive GIP impairs oral glucose tolerance and protects from diet-induced obesity and insulin resistance in mice." (PMID 34260412, 2021). "Thus, we cannot exclude that the absolute number of CCK-, PYY- and GIP-positive cells is enhanced in obesity." (PMID 33037328, 2021). "Gastric inhibitory polypeptide (GIP) is an obesity-promoting factor that acts on adipocytes." (PMID 33498462, 2021). "Therefore, through different mechanisms, both diet-induced obesity and aging act on the gut to increase GIP reserves for secretion into circulation." (PMID 34660576, 2021). "However, it seems that GIP is of significant importance in the development of obesity and its complications, through interactions with various body organs." (PMID 32069846, 2020). "Furthermore, the incretin hormone GIP enhances lipid uptake into adipose tissue, an action which appears impaired in subjects with obesity." (PMID 32663193, 2020). "In fact, GIP had for a long time and for many reasons been considered “the obesity hormone”; for instance, its secretion is enhanced by intake of fatty meals, and GIP infusions in experimental animals were reported to enhance chylomicron clearance and fat deposition." (PMID 32459834, 2020). "The purpose of this review is to summarise the physiological effects as well as the therapeutic implications of the gut hormones glucagon-like peptide-1 (GLP-1), oxyntomodulin, peptide YY (PYY), and glucose-dependent insulinotropic peptide (GIP) in the treatment of obesity and type 2 diabetes." (PMID 32436022, 2020). "In this study, the aim was to investigate whether exaggerated secretion of GIP in obesity may affect the markers of liver injury and liver targeted FGFs." (PMID 32069846, 2020). "The levels of leptin, GIP, and neuropeptide showed sex-dimorphism in obesity." (PMID 33644105, 2020). "Subjects with low GIP, despite obesity, seemed to be insulin sensitive and normolipemic." (PMID 32069846, 2020). "Altogether, rather than promoting weight loss, it was anticipated that GIP actions would promote weight gain and that a rational approach to obesity therapy therefore might be application of a GIP antagonist." (PMID 32459834, 2020). "However, GIP possesses other properties which make it unpromising as a therapy for diabetes and obesity." (PMID 32436022, 2020). "A link between GIP and obesity was made just over a decade after its first isolation, as it was suggested that the hormone could promote the deposition of these lipids in adipose tissue." (PMID 33339298, 2020). "Moreover, GIP levels are increased in older people, and in subjects with T2D and obesity, and correlate with levels of fasting and postprandial TGs." (PMID 32663193, 2020). "We hypothesized that elevated GIP levels in obesity may affect markers of liver injury through microRNAs." (PMID 32069846, 2020). "Thus, inflammation of adipose tissues and hypersecretion of GIP stimulate each other, resulting in a vicious circle of worsening insulin resistance and obesity." (PMID 31509948, 2019). "Moreover, in a mice model of partial reduction of GIP secretion, high-fat diet alleviated obesity and lessened the degree of insulin resistance, accompanied by higher fat oxidation and energy expenditure." (PMID 31412576, 2019).